CCDC127 (coiled-coil domain containing 127)
Description:
Regulates lipid droplet homeostasis. May be involved in the adipocyte differentiation.
Synonyms: FLJ25701
Tractability: PROTAC: ubiquitination databases record sites on it; its protein half-life has been measured.
Gene: Protein-coding gene on chromosome 5 (196,868 to 218,153, reverse strand). Ensembl gene ENSG00000164366.
Subcellular location: Mitochondrion outer membrane
Subcellular location (Human Protein Atlas): Nucleoli fibrillar center; Nucleoplasm
Gene Ontology:
Biological process: lipid homeostasis
Cellular component: mitochondrial outer membrane; mitochondrion
Genetic constraint (gnomAD): Loss-of-function variants: 5 observed, 7.27 expected, observed/expected ratio (o/e) 0.69, 90% interval 0.36 to 1.43. That is too few expected variants to judge how well the gene tolerates losing a copy. Missense variants: 268 observed, 300.05 expected, observed/expected ratio (o/e) 0.89, 90% interval 0.81 to 0.99. Synonymous variants: 98 observed, 112.07 expected, observed/expected ratio (o/e) 0.87, 90% interval 0.74 to 1.03.
Homologues: Orthologues: chimpanzee CCDC127 (99% identical), macaque CCDC127 (96% identical), dog CCDC127 (89% identical), rabbit CCDC127 (88% identical), guinea pig CCDC127 (85% identical), pig CCDC127 (85% identical), mouse Ccdc127 (83% identical), rat Ccdc127 (80% identical), tropical clawed frog ccdc127 (61% identical), zebrafish ccdc127a (51% identical), zebrafish ccdc127b (50% identical).